EZH2 (enhancer of zeste 2 polycomb repressive complex 2 subunit)
Diseases named in the same sentence as EZH2 in open-access papers (continued):
Sharing a sentence is not in itself a finding about the gene and the disease.
cancer (continued). "These non-canonical roles of EZH2 are not well characterized and if they play any role in cancer is currently unknown." (PMID 36359771, 2022). "The drugs, which received FDA approval for cancer treatment since 2011, inhibit the catalytic activity of such enzymes as steroid 17alpha-monooxygenase (CYP17A1), poly (ADP-ribose) polymerases (PARPs), thymidylate synthase (TS), topoisomerase (TOP) and enhancer of zeste homolog 2 (EZH2)." (PMID 35408658, 2022). "In summary, we demonstrated that EZH2/JARID2 has a significant and specific preference to bind to the highly expressed and cancer-related genes in the HepG2 cell line, which may partially explain the contribution of EZH2/JARID2 in the carcinogenesis and progression of HCC." (PMID 36578923, 2022). "However, the molecular mechanism of EZH2’s non-histone-mediated function in cancer remains poorly understood." (PMID 35955891, 2022). "One such lncRNA is ABHD11-AS1, which was reported to bind with EZH2 (Enhancer of Zeste Homolog 2), a catalytic subunit of PRC2 complex which maintains transcriptional repression through methylation of ‘Lys-9’ (H3K9me) and ‘Lys-27’ (H3K27me) of histone H3 in cancer." (PMID 35314614, 2022). "Indeed, efficacy of EZH2 inhibitors in malignant rhabdoid tumours is dependent on the activity of NSD1, reinforcing the importance of this balance of Polycomb and H3K36me2 domains across different cancers." (PMID 36105358, 2022). "However, Ezh2 also promotes gene expression in cancer cells without being dependent on its methyltransferase activity." (PMID 34764950, 2021). "Interestingly, existing evidence also revealed that the dysfunction of the PRC2 complex comprising of subunits such as EZH2, SUZ12, and EED could expedite abnormal hypermethylation of H3K27 which induces carcinogenesis in a wide array of cancers." (PMID 33882457, 2021). "Accordingly, reactivation of SLFN11 expression by epigenetic drugs targeting DNA methylation, histone deacetylase (HDAC), and histone methyltransferase EZH2 (Enhancer of zeste homolog 2) can reverse the chemoresistance of cancer cell lines that do not express SLFN11." (PMID 34572827, 2021). "In addition, EZH2, which was recruited by PVT1, could act as an oncogenic gene in several types of cancer." (PMID 33910638, 2021). "Additionally, both EZH2 and YY1 have been reportedly overexpressed in most cancer types; therefore, the YPB and OPB peptides can very likely exhibit inhibitory activities against other cancers." (PMID 34065631, 2021). "Since SOX4 regulates EMT of cancer cells by controlling EZH2 expression, we investigated whether miR-1251 could modulate the protein expression of EMT-related markers, SOX4 and EZH2 in PC cells." (PMID 34055896, 2021). "JMJD3 could be targeted in nonresistant cancer cells, and EZH2 in both nonresistant cancer cells and estrogen-resistant cancer cells, to limit BCL2 activation." (PMID 33478063, 2021). "In the mechanism of EZH2-mediated activation of Wnt/β-catenin signal to promote carcinogenesis, EZH2 acts as a transcription repressor, inhibiting Wnt antagonists by reducing the acetylation of H3K27, thereby promoting the development of different types of cancers." (PMID 34335707, 2021). "However, we strongly believe that our data holds novelty as to the best of our knowledge no previous studies have shown high histone methylation and EZH2 induction in E.C.M. detached cancer cells." (PMID 33531586, 2021). "Because EZH2 was documented to physically interacts and cooperate with E2F1 to stimulate the expression of a group of genes involved in cancer progression, we thus tested by co-immunoprecipitation whether such an interaction occurs in four different PAH-PASMC cell lines." (PMID 33803922, 2021).
cancer (continued). "While therapeutic targeting of PcG has not been extensively explored in any of these cancers, recent studies in pancreatic cancer indicate that targeting EZH2 or BMI1 may be effective in certain aggressive subtypes or cell populations." (PMID 34617019, 2021). "However, mounting evidence indicates that EZH2-mediated H3K27 trimethylation and subsequent gene silencing is not sufficient to account for all functions of EZH2 in cancer." (PMID 33803922, 2021). "A nonclassical regulatory mechanism of Ezh2 exists in cancer cells." (PMID 34764950, 2021). "Initial T cell activation is known to trigger EZH2 expression, however, whether this induction occurs to a similar extent in cases of chronic antigen stimulation like cancer has not been explored." (PMID 33117406, 2020). "However, further studies are warranted to evaluate effects of these agents on EZH2’s noncanonical functions in cancer cells." (PMID 33327550, 2020). "Manipulation of EZH2/PRC2 may, therefore, be a promising avenue for cancer therapy." (PMID 32883335, 2020). "Many other epi-drugs (e.g. JQ1, LSD1 inhibitors, and EZH2 inhibitor) in combination with anti-PD1 therapy, have been revealed that they can increase anti-tumour immune response via enhancing T-cell persistence in different cancers, such as lung cancer, TNBC, and lymphoma, etc." (PMID 32340605, 2020). "Therefore, EZH2 is related to many human diseases, including NAFLD, as well as cancer." (PMID 33207561, 2020). "This may explain why there is not any successful clinical trial targeting EZH2-PTMs for anti-cancer treatment to be carried out until now." (PMID 33308321, 2020). "Given the fact that EZH2 plays a PRC2- and methylation-independent role in cancer and many cancers do not respond to EZH2 enzymatic inhibitors, triggering EZH2 degradation may be a novel method to inhibit EZH2." (PMID 32723346, 2020). "In contrast, proteins that promote various cancer malignant properties, including CCND1, ERBB2, SNAIL, SLUG, phosphorylated STAT3 (p-STAT3), FAK, FOXM1, ETS1, YAP, HES1, and OCT4, were all significantly downregulated, an indication of reduction of malignancy in the cancer cells after EZH2 knockdown." (PMID 31130994, 2019). "In addition to histone, many other non-histone proteins also methylated by EZH2, and the interaction between EZH2 and these non-histone substrates plays important role in the development and progression of a variety of cancers." (PMID 31481081, 2019). "Here, we showed that Ezh2 inhibition by DZNEP could reduce Doc-induced gene expression of cancer stem cell markers (Nanog, CD44 and Sox2), supporting the notion that Ezh2 acts on these genes independent of PRC2 complex." (PMID 30621625, 2019). "Therefore, the combination of EZH2 and IFN-gamma -targeted therapy could represent a potential strategy in the treatment of patients with advanced cancer driven by MYC." (PMID 31366128, 2019). "Moreover, reduced EZH2 led to significantly reduced binding of LSD1, HDAC1, and DNMT1 to promoter regions of CDH1, CDKN1A, NEUROD1, and TUBB3, in agreement with increased transcription of these genes in cancer cells after EZH2 knockdown." (PMID 31130994, 2019). "The downregulation of EZH2 observed in our cell lines, could be produced by the reduced expression of CDK1 after LUCAT1 knockdown that thus promotes the aberrant cell transformation to cancer cells." (PMID 31591432, 2019). "However, the molecular mechanisms by which EZH2 inhibitors inhibit the growth of cancer cells are not fully understood." (PMID 31410199, 2019). "Interestingly, inhibition of EZH2 activity by EPZ-011989 also induced EZH2 protein down-regulation concomitantly with an increased expression of the known EZH2 target gene early growth response 1 (EGR1), a multifunctional transcription factor thought to act as a cancer suppressor." (PMID 31331120, 2019).
cancer (continued). "Among them, histone methyltransferase enhancer of zeste homolog 2 (EZH2), the enzyme that catalyzes the tri-methylation of lysine 27 on histone H3 (H3K27me3), is a known, key epigenetic regulator and EMT inducer, which participates in the metastasis of a variety of cancers." (PMID 30093632, 2019). "Combining PTX with EZH2 inhibitor GSK126 significantly reduced the dosage of GSK126 required to obtain a significant growth inhibition and cell death, suggesting that PTX could complement the treatment of cancers with high levels of EZH2 expression." (PMID 30555699, 2018). "Thus, derepression of these genes using selective EZH2 enzymatic inhibitors or disruptors of PRC2 stability are likely to improve clinical outcomes, and are currently being explored in preclinical or clinical studies for cancer therapy." (PMID 30619315, 2018). "In cancer, EZH2 does not repress self-renewal that is retained." (PMID 29853899, 2018). "This lack of immune Th1 competence paralleled the increase in EZH2 positivity by cancer cells." (PMID 30510965, 2018). "Our findings may have significant translational implications since aberrant EZH2 activity contributes to cancer and PARP1 inhibitors are in clinical trials, and we show that combinatorial treatment with an EZH2 and PARP1 inhibitor enhances PARP-mediated genotoxicity in cells from cancer patients." (PMID 29535829, 2018). "We also report that new cancer therapeutic strategies are targeting KDM6B and EZH2, but the specificity of these treatments may be increased by learning more about the mechanisms of action of these enzymes and their specific partners or target genes in different cancer types." (PMID 34991274, 2018). "Though no EZH2 inhibitor is yet widely available in clinical settings, one such agent, tazemetostat, is currently being investigated in clinical trials as a treatment for certain cancers." (PMID 29740453, 2018). "However, from a therapeutic perspective, it is not clear if the EZH2 targets are essential for all cancer types." (PMID 28410242, 2017). "Negative-modulation of these miRNAs promotes EZH2 level and may have implications in cancer progression." (PMID 28561778, 2017). "In addition, both EZH2 inhibition and knockdown (KD) dramatically decrease CSC tumorigenicity, supporting the notion that EZH2 may serve as a novel CSC marker and a potential target for cancer therapy." (PMID 28415635, 2017). "Due to the large number of these proteins, only those highly relevant to cancer are described, with a particular focus on histone H3 lysine 79 (H3K79) methyltransferase DOT1L, H3K4 targeting mixed lineage leukemia (MLL) and lysine-specific demethylase 1 (LSD1), and H3K27 methyltransferase EZH2." (PMID 27316347, 2016). "In addition, negative association of EZH2 and MT1/MT2A expression is found in cancers including HCC." (PMID 26973856, 2016). "EZH2 inhibits the expression of tumor suppressor RAD51 which participates in DNA repair leading to genomic instability and increases some oncogene expression such as RAF1 which activates ERK and Wnt-β-catenin pathway to promote cancer cell survival and proliferation, and expands BCSCs." (PMID 26349457, 2016). "Finally, it seems that EZH2 catalytical activity does not have the most significant role for an increased rate of growth in some SWI/SNF-mutant cancers." (PMID 27239242, 2016). "In addition, the negative association of EZH2 and MT1/MT2A genes in cancer cell lines and tissues was found in public gene expression database." (PMID 26973856, 2016). "No EZH2 inhibitors have been approved for the treatment of human cancers to date." (PMID 27502594, 2016). "Furthermore, pharmacologic interference of EZH2 function induces selective apoptosis in cancer cells but not in normal cells, making it an attractive anti-cancer drug target." (PMID 26265454, 2015).
cancer (continued). "Therefore, the Y641N or Y641S mutations in the EZH2 SET domain do not affect EZH2 protein levels, but result in a hyperactive enzyme causing aberrantly increased H3K27me3 in the EZH2GOF DLBCL cells compared to other cancer cell lines." (PMID 25605023, 2015). "Furthermore, histone deacetylase (HDAC) inhibitors reduce stemness of multiple cancer cell types and pharmacological inhibition of EZH2 has been found to induce apoptosis of cancer stem cells but not normal ES cells." (PMID 27158195, 2015). "The only up-regulated gene, EZH2, identified in our study was not part of the Ramaswamy signature though the gene was up-regulated with respect to metastasis in the Ramaswamy Multi-cancer dataset comparing primary tumors versus metastases in Oncomine with a Q-value of 0.05." (PMID 21736749, 2011). "However, EZH2 and p27 levels did not significantly correlate in individual cancers (n = 68) on a per patient basis, i.e. in tumors derived from the same patient." (PMID 21765901, 2011). "Interestingly, in Normal tissues from 18 non-cancer patients, we found that transcription of Cbx7 was positively correlated with those of Ring1, Bmi1, Mel18, and Phc2, but not with those of Cbx8 and Ezh2 (Ps<0.01)." (PMID 21060834, 2010). "In the 53 ESCC cases with high EZH2 expression, an average of 55.0% of the ESCC cells stained positively with H3K27me3 antibody, a percentage of cancer cells that was significantly larger than that (43.3%) in the remaining 45 cancers with a low expression of EZH2 (P = 0.036)." (PMID 20028503, 2009). "Given the involvement of EZH2 in CDKN1C repression, we took the advantage of Oncomine microarray database and asked whether their expression levels are reversely correlated in human cancer." (PMID 19340297, 2009). "Furthermore, we confirmed the pharmacological efficacy of the EZH2 inhibitor SHR2554 and demonstrated a synergistic effect when combined with the HDAC inhibitor Chidamide through commercial TCL cell lines, in vivo cell-derived xenograft, and patient-derived xenograft cancer models." (PMID 40659662, 2025). "However, EZH2 free from other components of PRC2 might have a noncanonical function for cancer progression." (PMID 41413688, 2025). "For instance, targeting of EZH2, the catalytic subunit of the PRC2, is currently under evaluation in several phase 1/2 clinical trials and therefore could potentially offer previously unknown epigenetic therapeutic options for RBNSig-high cancers with EZH2 dysregulation." (PMID 40138429, 2025). "However, recent reports have disclosed that unlike DZNep, which is thought to deplete PRC2 subunits in cancer cells by way of an indirect mechanism, other EZH2 inhibitors, such as GSK343, are able to directly and selectively inhibit PRC2 enzymatic activity, probably increasing their efficacy." (PMID 39204206, 2024). "Additionally, unlike HIF1α or EZH2, GLI-1 was the sole transcription factor activated by integrin-linked focal adhesion kinase, indicating GLI-1 as a key driver of the EZH2-integrin α11 axis operating for cancer stem cell survival and EMT." (PMID 38664825, 2024). "Moreover, we found that combined treatment of cells with SAHA and EZH2 inhibitors induced cellular senescence via the suppression of CCF production, resulting in the inhibition of SASP secretion and the enhancement of the cancer-suppressing effect of SAHA in SCLC cells." (PMID 37543653, 2023). "However, the interaction between EZH2 and miR-34a-5p in malignant tumors has not yet been reported." (PMID 37988356, 2023). "Therefore, the combination of drugs targeting the pro-oncogenic role of EZH2 in tumoral cells and its role promoting an immunosuppressive TME, with immunotherapy, could have a synergistic effect, improving the therapeutic responses of some types of cancer." (PMID 36135315, 2022). "Current EZH2 inhibitors may not be highly effective in certain cancer types." (PMID 35509102, 2022).
cancer (continued). "However, targeting EZH2 with methyltransferase inhibitors has not always proven to be beneficial in clinical trials, partially because of the EZH2 methyltransferase-independent functions in promoting cancer development." (PMID 35538070, 2022). "Therefore, CELF2, similar to EZH2, was defined as a negative prognostic marker for HNSCC; however, the association of this cancer to PNI is still unknown and will need to be validated." (PMID 35571032, 2022). "However, they found that this EZH2 inhibition was independent of its methyltransferase activity, revealing that EZH2 may play a role in cancer beyond its enzymatic epigenetic reprogramming abilities." (PMID 36684449, 2022). "Supporting the idea that BAP1 mutant cancers actually confers loss of PcG repression rather than the previously assumed hyperactivation of PRC1 and PRC2 activities, is the lack of response of BAP1 mutant mesothelioma patients to the EZH2 inhibitor Tazemetostat." (PMID 36105358, 2022). "A clear outcome of the proliferation and viability assays was that the impact of EZH2 inhibition on E.C.M. detached cancer cells was independent of cell and cancer types, further suggesting that at least this might be a common mechanism for a variety of different cancer cells of different origins." (PMID 33531586, 2021). "In addition to reporting that DLC1 protein is a new critical substrate for cytoplasmic EZH2, this study provides a rational approach for combination molecular targeted agent cancer treatment by non-genetically reactivating a tumor suppressor protein, leading to potent antitumor activity." (PMID 34862367, 2021). "Interestingly, Ili-A suppressed the binding of EZH2 to promoter regions in AR/serine/threonine polo-like kinase-1/aurora kinase A. Moreover, Ili-A could enhance the anticancer activity of enzalutamide in CRPC cancer models." (PMID 34776951, 2021). "Therefore, given the observed synergy between SM or TNFα with EZH2 inhibitors such as UNC1999 and GSK343, which are in clinical development, we propose that such combination therapy could be further exploited to target other cancer types." (PMID 30854231, 2019). "Thus, Ezh2 has multiple essential biological effects, and it is not surprising that its function (and often dysfunction) plays an important role in various diseases, especially in cancer." (PMID 29335012, 2018). "Inhibitors targeting the histone methyltransferases DOT1L and EZH2, as well as the demethylase KDM1 (also known as LSD1), have recently entered the first stages of clinical trials in cancer therapy and might hold the potential to modulate the cancer-immune system axis." (PMID 28545238, 2017). "Although such talin-related function of EZH2 has not been identified in cancer cells, it would be important to investigate whether such mechanism mediated by EZH2 might affect cancer cell adhesion and migration and might be critical for the regulation of invasion and metastasis." (PMID 27793053, 2016). "Moreover, the mechanistically interaction between EZH2 and DNMT1 regulated their downstream targets, thereby controlling DNA methylation and/or transcriptional repressed micoRNAs (miRNAs) expression, which contributed to growth and progression in several cancer types." (PMID 27421653, 2016). "Since EZH2 suppresses the differentiation of normal embryonic stem cells by decreasing the expression of lineage specifying factors, it is not surprising that it is highly expressed in cancer stem cell (CSC) populations maintaining their survival and inhibiting their differentiation." (PMID 27793053, 2016). "Therefore, inhibition of EZH2/H3K27 methylation may not be sufficient to correct the overall effects by PRC2-mediated gene silencing in these cancer cells." (PMID 25359765, 2014).